CDKN2A (cyclin dependent kinase inhibitor 2A)
Diseases named in the same sentence as CDKN2A in open-access papers (continued):
Sharing a sentence is not in itself a finding about the gene and the disease.
glioblastoma (continued). "CDKN2A inhibition led to a significant increase in cell viability and decreased sensitivity to carmustine treatment in U87 glioblastoma cells." (PMID 38438773, 2024). "MSP analysis showed significantly higher CDKN2A promoter methylation levels in U87 glioblastoma cells compared to normal human astrocytes (NHA)." (PMID 38438773, 2024). "The downregulation of CDKN2A in glioblastoma cells, possibly mediated by promoter methylation, contributes to increased cell viability, chemoresistance, enhanced self-renewal capacity, and maintenance of pluripotency." (PMID 38438773, 2024). "To investigate the impact of CDKN2A on these proteins in U87 glioblastoma cells, we performed western blot analysis." (PMID 38438773, 2024). "Cell viability assays and carmustine sensitivity tests were conducted to assess the impact of CDKN2A modulation on glioblastoma cell viability and drug response." (PMID 38438773, 2024). "We also explored the epigenetic regulation of CDKN2A, focusing on promoter methylation as a potential mechanism for its downregulation in glioblastoma." (PMID 38438773, 2024). "It has been also shown that glioblastoma cell lines retain the same homozygous deletions in the cyclin-dependent kinase inhibitor 2A (CDKN2A) gene, as the original tumors." (PMID 38966179, 2024). "Sphere formation assays and western blot analysis were performed to investigate the role of CDKN2A in glioblastoma stem cell (GSC) self-renewal and pluripotency marker expression." (PMID 38438773, 2024). "Third, although the study provides important insights into various aspects of CDKN2A in glioblastoma, there are still unanswered questions." (PMID 38438773, 2024). "Specifically, we examined the expression levels of CDKN2A in glioblastoma cells and assessed its impact on cell viability, chemosensitivity, self-renewal capacity, and pluripotency." (PMID 38438773, 2024). "Our findings demonstrate that CDKN2A is significantly downregulated in glioblastoma cells, suggesting its potential role in glioblastoma development and progression." (PMID 38438773, 2024). "Comparing normal human astrocytes (NHA) with U87 glioblastoma cells, we found significantly reduced CDKN2A expression in the U87 cells." (PMID 38438773, 2024). "CDKN2A overexpression reduces viability and enhances sensitivity to carmustine in U87 glioblastoma cells." (PMID 38438773, 2024). "Downregulation of CDKN2A has been reported in glioblastoma cell lines and patient samples, implicating its tumor-suppressive function." (PMID 38438773, 2024). "One systematic review reported that glioblastoma patients had shorter PFS in the presence of CDKN2A homozygous deletion in two studies (median values, 16 vs. 30 months) and shorter OS in four studies (median values, 38 vs. 86 months)." (PMID 39457569, 2024). "Quantitative reverse transcription PCR (qRT-PCR) analysis was performed to evaluate CDKN2A expression in U87 glioblastoma cells compared to normal human astrocytes (NHA)." (PMID 38438773, 2024). "To assess the impact of CDKN2A on glioblastoma cell viability, we performed MTT assays at different time points (0, 24, 48, 72 h) following CDKN2A knockdown (si-CDKN2A) or overexpression (CDKN2A)." (PMID 38438773, 2024). "This study aimed to investigate the expression and functional implications of CDKN2A, a key tumor suppressor gene, in glioblastoma cells, building upon the existing background of knowledge in this field." (PMID 38438773, 2024). "The role of homozygous CDKN2A/B deletion as an independently prognostic biomarker for worse survival among IDH-wildtype glioblastoma has been indicated, but the data concerning other genes are very controversial." (PMID 39684714, 2024).
glioblastoma (continued). "The observed reduction in CDKN2A expression in U87 glioblastoma cells is consistent with previous reports highlighting the tumor-suppressive function of CDKN2A in glioblastoma." (PMID 38438773, 2024). "The findings from this study contribute to our understanding of the molecular underpinnings of glioblastoma and provide insights into the potential therapeutic targeting of CDKN2A." (PMID 38438773, 2024). "Further research is needed to determine the exact role and potential applications of CDKN2A in glioblastoma development and treatment." (PMID 38438773, 2024). "This suggests that CDKN2A overexpression reduces the self-renewal capacity of U87 glioblastoma cells." (PMID 38438773, 2024). "The results presented in this study provide compelling evidence regarding the functional significance and regulatory mechanisms of CDKN2A in glioblastoma." (PMID 38438773, 2024). "Overall, our study provides comprehensive insights into the functional significance and regulatory mechanisms of CDKN2A in glioblastoma." (PMID 38438773, 2024). "While this is supported by other studies that demonstrated p16-negative tumours on IHC had a high negative predictive value for CDKN2A HD in adult and paediatric morphologic glioblastomas, other studies reported p16/CDKN2A discordance with the IHC method." (PMID 37504251, 2023). "Our goal is to identify CDKN2A specific qualitative imaging biomarkers in glioblastomas using a new informatics workflow that enables rapid analysis of qualitative imaging features with Visually AcceSAble Rembrandtr Images (VASARI) for large datasets in PACS." (PMID 38135704, 2023). "These two tumors had the combination of trisomy chromosome 7 and monosomy chromosome 10 along with genetic alterations typical of conventional IDH-wildtype glioblastoma (e.g., TERT promoter mutation, CDKN2A/B homozygous deletion, EGFR amplification)." (PMID 38079020, 2023). "It is worth mentioning that the condition of CDKN2A deletion has been reported in other types of human cancers including glioblastoma, sarcoma, and gastric carcinoma." (PMID 37626750, 2023). "Progression to anaplastic oligodendroglioma is associated with additional genetic changes, such as loss of chromosome 9p, resulting in deletion of the CDKN2A tumor suppressor gene and the same TERT promoter mutations detected in glioblastoma." (PMID 36768856, 2023). "Abemaciclib was used on the basis of homozygous CDKN2A/B deletion according to the results of the interim analysis of the Individualized Screening Trial of Innovative Glioblastoma Therapy (INSIGhT)." (PMID 35953681, 2023). "They proposed that the addition of bevacizumab should be considered in patients with CDKN2A HD glioblastoma." (PMID 37504251, 2023). "Molecular profiles similarly indicated a poor-risk biological cohort including predominance of IDH-1 wild type (85.7%), MGMT unmethylated (57.1%) tumors with EGFR, PTEN, and CDKN2A profiles in keeping with molecular glioblastoma." (PMID 36402744, 2023). "Evidence suggests that CDKN2A/B deletion is one of the characteristics of astrocytomas and that chr7 gain & chr10 loss and EGFR amplification are characteristics of glioblastomas." (PMID 37274274, 2023). "This incorporation of informatics tools into one software package is the basis for a relational database approach for brain tumor analysis and was critical for our phenotypic characterization of glioblastomas based on CDKN2A HOMDEL status." (PMID 38135704, 2023). "They lacked EGFR amplification, lacked combined trisomy of chromosome 7 plus monosomy of chromosome 10, and only rarely had TERT promoter mutation or CDKN2A homozygous deletion, which are hallmarks of conventional IDH-wildtype glioblastoma." (PMID 38079020, 2023).
glioblastoma (continued). "Moreover, another study found that glioblastoma (GBM) xenograft lines with CDKN2A expression and either RB mutation or CDK4 amplification were resistant to palbociclib." (PMID 35892870, 2022). "To better characterize the effects of CDKN2A homozygous deletion on survival, we performed subgroup analysis of IDHwt glioblastoma patients with CDKN2A copy deletions (CDKN2Adel) and with intact CDKN2A genes (CDKN2Aint)." (PMID 36380219, 2022). "We identified a second glioblastoma case from the UCSF500 cohort with TERTp duplication, gain of chromosome 7, loss of chromosome 10 and homozygous deletion of CDKN2A as well as an NF1 frameshift mutation." (PMID 36114166, 2022). "This latter can gain Rb1 loss/mutation, CDK4/6 amplification, PDGFRA amplification, or lose CDKN2A and, over the years, becomes IDH-mutated secondary glioblastoma." (PMID 34422883, 2021). "Primary glioblastomas typically display EGFR overexpression, CDKN2A (p16) deletions, PTEN (MMAC1) mutations, and MDM2 amplification." (PMID 33804731, 2021). "Mutations in the cell cycle G1 phase genes CDKN2A/2B, CDK4, and RB1 were mutually exclusive in this series, except for two heterozygous germline RB1 point mutations, and were present in 79.3% of glioblastoma IDH-wild-type cases." (PMID 34572759, 2021). "According to the 2016 WHO classification of brain tumors of the central nervous system, IDH-wildtype glioblastomas show homozygous deletion of CDKN2A/B in approximately 60%." (PMID 33876327, 2021). "With the analysis of database Glioblastoma Multiforme (TCGA, Provisional), we found that the deletion rate of CDKN2A locus 9p21.3 was up to 57.4%, and the deletion rate of CDKN2B locus 9p21.3 was up to 56%." (PMID 32860670, 2020). "CDK6 is a validated target in the treatment of Glioblastoma, a kind of brain tumor that is characterized by a high frequency of CDKN2A/CCND2/CDK4/CDK6 pathway dysregulation." (PMID 32858868, 2020). "It has been shown that the region is significant for glioblastomas and highly recurrent homozygous deletions of CDKN2A/B genes were established." (PMID 30871102, 2019). "Further molecular testing illustrated features more consistent with glioblastoma: multiple large chromosomal aberrations including loss of whole chromosome 1 and 2q; gain/amplification of MYCN, MET, and CDK4; loss of CDKN2A/B; and an ATRX mutation." (PMID 30738431, 2019). "The RTKII group corresponds to the classic group of adult glioblastomas and is characterized by the high frequency of EGFR amplification, CDKN2A deletion, chromosome 7 gain, and chromosome 10 loss." (PMID 30279357, 2018). "Bi-allelic inactivation of genes is common in cancer, including ATM in chronic lymphocytic leukemia, CDKN2A and CDKN2B in glioblastoma, and are indicative of loss of function of key tumor suppressor genes." (PMID 28234347, 2017). "Somatic CDKN2A deletions are common in both diffuse lower-grade astrocytomas and primary glioblastomas." (PMID 28699883, 2017). "Glioblastomas have a high frequency of mutations in the TERT promoter and CDKN2A locus that are expected to render them resistant to both replicative and oncogene-induced senescence." (PMID 28526854, 2017). "For example, the RB1 pathway is inactivated in all glioblastoma tumors but is caused either by somatic RB1 mutations, CDKN2A/B mutations, or CDK4 amplification." (PMID 27126562, 2016).
glioblastoma (continued). "Eighty percent (12/15) of BRAF mutated glioblastomas concurrently harbored CDKN2A homozygous deletion, compared with 26.4% (19/72) of BRAF wild-type glioblastomas (p = 0.0002)." (PMID 26452024, 2016). "BRAF-V600E identified a clinically favorable subset of glioblastomas with younger age, frequent CDKN2A homozygous deletion, and was more amendable to surgical resection." (PMID 26452024, 2016). "CDKN2A-null mice astrocytes have high proliferation and are used as a model for glioblastoma development." (PMID 25954815, 2015). "After overexpression of CDKN2A in glioblastoma cell lines T98G, U87-MG and SW1783 MG, the expression of cyclin D1 was decreased." (PMID 21843312, 2011). "In contrast, 7/13 glioblastomas with hemizygous deletions of CDKN2A and 8/11 glioblastomas with hemizygous deletions of CDKN2B showed no or weak expression." (PMID 9000591, 1997). "Oligo Cdkn2a tumors displayed metabolic and transcriptional changes associated with IDH and CIC mutations, and single cell sequencing identified a bias towards oligodendrocyte differentiation compared to an IDH wild-type glioblastoma mouse model." (PMID 42239081, 2026). "Cox proportional hazards (CPH) analysis of recurrently comutated genes revealed CDKN2A/B homozygous loss was associated with worse OS in NF1-mutant but not NF1 wild-type glioblastomas." (PMID 40985888, 2025). "Targeted DNA sequencing of somatic NF1-mutant, IDH wild-type glioblastomas identifies CDKN2A/B loss as a negative prognostic factor." (PMID 40985888, 2025). "Recent studies have begun to shed light on the role of CDKN2A in glioblastoma pathogenesis." (PMID 38438773, 2024). "Research on the role of CDKN2A deletion in patients with glioblastoma is rare." (PMID 39457569, 2024). "Notably, our study elucidates the impact of CDKN2A modulation on glioblastoma cell viability and sensitivity to the chemotherapeutic agent carmustine." (PMID 38438773, 2024). "By elucidating the role of CDKN2A in glioblastoma cell behavior and its interaction with important signaling pathways, we aim to pave the way for the development of novel treatment strategies that could improve patient outcomes in this devastating disease." (PMID 38438773, 2024). "Consequently, the downregulation of CDKN2A expression is anticipated in U87 glioblastoma cells as a result of this increased methylation." (PMID 38438773, 2024). "CDKN2A expression was significantly reduced in glioblastoma cells compared to NHA." (PMID 38438773, 2024). "In primary glioblastomas, there is often loss of the INK4A/ARF (cyclin-dependent kinase inhibitor 2A/B—CDKN2A) gene locus, mutations in the phosphatase and tensin homolog deleted on the chromosome 10 (PTEN) gene, and amplification or loss of the epidermal growth factor receptor (EGFR) gene." (PMID 39770078, 2024). "By contrast, in spheroids derived from glioblastoma 14-60-4, the Cdkn2a and Mki67 mRNA levels were unchanged, and the transcription rates for Pik3cg, Pten, and Abcb1b increased dramatically, while Sox2 expression decreased, reaching minimal values recorded in the whole experiment." (PMID 38672482, 2024).
glioblastoma (continued). "Furthermore, we investigated the effect of CDKN2A on the sensitivity of U87 cells to carmustine, a chemotherapeutic agent commonly used in glioblastoma treatment." (PMID 38438773, 2024). "Therefore, a more comprehensive understanding of the complete regulatory mechanisms of CDKN2A in glioblastoma is warranted." (PMID 38438773, 2024). "Firstly, the expression downregulation of CDKN2A observed in glioblastoma cells may not encompass all the functions and regulatory mechanisms of CDKN2A in glioblastoma, as the study focuses primarily on its role in methylation." (PMID 38438773, 2024). "CDKN2A downregulation is due to high promoter methylation in U87 glioblastoma cells." (PMID 38438773, 2024). "Moreover, in spheroids obtained from glioblastoma 35 and neuroma 46-1, these changes were predominantly unidirectional, and the most pronounced decrease was shown by the Cdkn2a and Mki67 genes involved in the regulation of proliferation and the cell cycle." (PMID 38672482, 2024). "CDKN2A inhibition impairs self-renewal capacity of U87 glioblastoma cells." (PMID 38438773, 2024). "Furthermore, our study provides insights into the involvement of CDKN2A in the regulation of self-renewal capacity and pluripotency in glioblastoma cells." (PMID 38438773, 2024). "The findings proved that the deletion of CDKN2A may play a significant role in glioblastoma-related venous thromboembolism (VTE)." (PMID 39682237, 2024). "For instance, the precise mechanisms of CDKN2A in glioblastoma development and progression remain unclear, as well as how these findings can be translated into therapeutic strategies." (PMID 38438773, 2024). "Understanding the regulatory mechanisms governing GSCs and their interaction with CDKN2A could provide crucial insights into glioblastoma progression and identify novel therapeutic strategies." (PMID 38438773, 2024). "Our study investigated whether qualitative imaging biomarkers for CDKN2A can be identified in glioblastomas on pre-operative MR images using standard imaging protocol, as this sub-classification of glioblastomas is currently not available." (PMID 38135704, 2023). "These tumors generally occur at a younger age compared to conventional glioblastomas and mostly lack the molecular hallmarks of conventional glioblastoma including EGFR amplification, trisomy 7 plus monosomy 10, TERT promoter mutation, and CDKN2A/B homozygous deletion." (PMID 38079020, 2023). "Therefore, a diagnosis of astrocytoma, IDH mutant, or CNS WHO grade 4 requires either morphologic features of a glioblastoma, namely necrosis or microvascular proliferation, or homozygous deletion of CDKN2A and/or CDKN2B." (PMID 37504251, 2023). "The mutation of the CDKN2A gene is extremely rare (3%), and its presence associated with clinical evolution has led some researchers to consider these tumors as an intermediate between IDH wildtype and mutant IDH glioblastoma." (PMID 36005160, 2022). "The lack of radiation dose response in TERTwt patients but not TERTmut patients also suggests that observations of dose response sensitivity in IDHwt glioblastomas may be dependent on particular genetic alterations, such as CDKN2A and TERT." (PMID 36380219, 2022). "Patients with CDKN2A copy loss (HR 2.963, p = 0.0037) or TERT mutated (HR 2.815, p = 0.0008) glioblastomas exhibited significant associations between radiation dose and OS, while CDKN2A and TERT wild type patients did not." (PMID 36380219, 2022). "The prognostic significance of MTAP deletion has not been previously well characterized, but our results suggest that MTAP deletion may potentially serve as a surrogate marker for CDKN2A deletion in prognostic evaluation of IDHwt glioblastoma patients." (PMID 36380219, 2022). "In IDHwt glioblastomas, CDKN2A, CDKN2B, and MTAP predict for poor prognosis." (PMID 36380219, 2022).